EML4 (EMAP like 4)
Diseases named in the same sentence as EML4 in open-access papers (continued):
Sharing a sentence is not in itself a finding about the gene and the disease.
lung adenocarcinoma (continued). "Among candidate co-operating events to be examined is the inactivation of SETD2, a histone methyltransferase recently reported to be mutated in EML4-ALK fusion-driven lung adenocarcinoma." (PMID 33761896, 2021). "Characteristics of the ‘203 primary resection lung adenocarcinoma specimens’ and correlations between the patients harboring EML4-ALK mutation." (PMID 32876329, 2021). "Approximately 3–7% of patients with lung adenocarcinoma have the echinoderm microtubule-associated protein-like 4 (EML4)/ALK fusion gene." (PMID 33435596, 2021). "Our latest study has showed that concomitant EGFR mutation and EML4-ALK rearrangement in lung adenocarcinoma was more frequent in multifocal lesions." (PMID 32375829, 2020). "There is therefore a need to generate isogenic lung adenocarcinoma cell lines expressing EML4-ALK variants in order to compare pathways activated in cells with the same genetic background." (PMID 28872581, 2017). "Among the alterations, rearrangement of the anaplastic lymphoma kinase (ALK) gene and echinoderm microtubule-associated protein-like 4 (EML4) occurs in approximately 5% of lung adenocarcinomas, representing the most frequent rearrangements." (PMID 28970558, 2017). "In general, the frequency of the EML4-ALK fusion gene in lung adenocarcinoma is relatively low compared with that of EGFR mutations in the Japanese population (6.7% and 45%, respectively)." (PMID 29212235, 2017). "The thyroid tumour was determined to be a metastasis from the lung adenocarcinoma because of the positive finding of EML4-ALK (variant 3a/3b was amplified) obtained using the RT-PCR method." (PMID 27872133, 2016). "To date, the EGFR and KRAS gene mutations, and the EML4-ALK fusion gene have been identified as major oncogenic driver mutations of lung adenocarcinomas." (PMID 26268359, 2015). "The rearrangement of the anaplastic lymphoma kinase (ALK) gene and echinoderm microtubule-associated protein-like 4 (EML4) gene occurs in approximately 5% of lung adenocarcinomas, leading to the overexpression of anaplastic lymphoma kinase." (PMID 25785456, 2015). "An additional factor that must be considered is that EML4–ALK fusions were detected in only about 5% of lung adenocarcinoma, and it was mutually exclusive to other EGFR mutations and K-ras mutations." (PMID 25003505, 2014). "EGFR mutations, K-ras mutations and EML4–ALK fusions have been shown to be primarily restricted to lung adenocarcinoma." (PMID 25003505, 2014). "Histologically, mucinous cribriform pattern is shown to be frequently associated with EML4-ALK positive lung adenocarcinoma." (PMID 23617234, 2013). "Examples include gefitinib for EGFR mutation-positive lung adenocarcinoma and crizotinib for EML4-ALK positive lung adenocarcinoma." (PMID 23617234, 2013). "On the other hand, echinoderm microtubule-associated protein-like 4 (EML4)-anaplastic lymphoma kinase (ALK) fusion gene in a subset of lung adenocarcinoma is related to mucinous cribriform histology." (PMID 23617234, 2013). "In patients with advanced lung adenocarcinoma (LADC) harboring the echinoderm microtubule-associated protein-like 4 (EML4) -anaplastic lymphoma kinase (ALK) rearrangement, targeted therapy typically demonstrates superior efficacy as an initial treatment compared to chemotherapy." (PMID 38380327, 2024). "ALK rearrangements occur in 3–5% of lung adenocarcinomas, consequent to an inversion on the short-arm of chromosome 2 joining its 3′ end with the 5′ end of the echinoderm microtubule-associated protein-like 4 (EML4), resulting in an EML4-ALK chimeric protein." (PMID 34915883, 2021).
lung adenocarcinoma (continued). "Besides, ALK fusions were firstly identified in 2007 and occurred in approximately 3–7% of all lung adenocarcinoma patients, and the most common form was echinoderm microtubule-associated protein-like 4/anaplastic lymphoma kinase (EML4-ALK)." (PMID 32677962, 2020). "The echinoderm microtubule-associated protein-like 4 (EML4)-anaplastic lymphoma kinase (ALK) fusion gene was identified for the first time in 2007 in a 62 year-old male patient with lung adenocarcinoma, ALK-rearrangements serve as a key oncogenic driver that occur in 3%–7% of patients with NSCLC." (PMID 29632648, 2018). "Interestingly, our study demonstrated that EGFR and EML4-ALK mutations were observed in 50% (11/22) of the lung adenocarcinoma patients." (PMID 26332764, 2015). "Herein, we present a CARE checklist-compliant case report documenting an EML4-ALK-fusion-positive lung adenocarcinoma patient with ovarian metastasis who demonstrated significant tumor regression and prolonged survival following lorlatinib treatment." (PMID 41261685, 2025). "Three lung adenocarcinoma samples with known EML4-ALK status as determined by qRT-PCR and FISH were analyzed for ALK protein expression using the D5F3/VENTANA and BP6165/LYNX480 PLUS immunohistochemical assays, respectively." (PMID 40017673, 2025). "In this study, we report, for the first time, a novel ELMOD3-ALK and EML4-ALK double fusion identified by next-generation sequencing (NGS) in a patient with lung adenocarcinoma." (PMID 40297141, 2025). "BRAF mutations occur in approximately 2–4% of patients with lung adenocarcinoma and are mutually exclusive of EGFR, KRAS, and EML4–ALK." (PMID 39995841, 2025). "initially reported the EML4-ALK fusion gene when they amplified a 3926-bp DNA fragment encoding a 1059 amino acid protein, the fusion protein EML4-ALK, in tumor tissue from a lung adenocarcinoma patient." (PMID 40071084, 2025). "This article reports the case of a long-term surviving patient with EML4/ALK translocated non–small cell adenocarcinoma of the lung in UICC8 stage IVA." (PMID 38960389, 2025). "Research has established that mutations in EGFR and KRAS, as well as EML4-ALK fusions, represent the most common driver alterations in lung adenocarcinoma." (PMID 41153394, 2025). "This case of EML4-ALK + lung adenocarcinoma with ovarian metastasis is extremely rare and provides valuable insights into the pathological, molecular research, and treatment strategies for such patients." (PMID 41261685, 2025). "The confirmed EML4-ALK lung adenocarcinoma samples were used as tissue controls containing positive tumor cells negative lymphocytes and interstitial fiber cells." (PMID 40017673, 2025). "In this study, we present a case of a 60-year-old female patient who was diagnosed with stage IIIA (cT2aN2aM0, ninth TNM stage) lower left lung adenocarcinoma harboring an EML4-ALK fusion." (PMID 40071084, 2025). "This case deepens our understanding of ALK+ NSCLC with diverse genomic alterations and provides insight into the new treatment of EML4-ALK+ lung adenocarcinoma with multiple gene fusions." (PMID 40052122, 2025). "Liver biopsy and genetic testing confirmed the diagnosis of stage IV EML4-ALK fusion-positive lung adenocarcinoma with ovarian and hepatic metastases." (PMID 41261685, 2025). "In conclusion, this is the first report of a novel SV2B-ALK and EML4-ALK double-fusion in a lung adenocarcinoma patient with extensive metastases." (PMID 39735595, 2024). "A study of lung adenocarcinoma demonstrated that EML4-ALK fusion can upregulate p-STAT3 levels, then p-STAT3 upregulates PD-L1 expression by binding to the CD274 promoter." (PMID 38426097, 2024). "A study discovered lung adenocarcinoma patients with EML4-ALK fusion have higher levels of PD-L1 on tumor cells than patients without EML4-ALK fusion." (PMID 38426097, 2024).
lung adenocarcinoma (continued). "We reported a third-line ensartinib therapy in a patient with lung adenocarcinoma who developed an acquired EML4-ALK fusion after sequential treatment with erlotinib and osimertinib." (PMID 39135785, 2024). "Inhibition of the HSP90 chaperone was evaluated in different lung adenocarcinoma cell lines representing the most relevant molecular alterations (EGFR mutations, KRAS mutations, or EML4-ALK translocation) and wild-type genes found in each tumor subtype." (PMID 37762133, 2023). "Fusion EML4:ALK, a known cancer driver prevalent in lung adenocarcinoma, has evidence of multiple transcript variant structures, and while microhomologies are found between the EML4 and ALK genes they tend to be distal from the fusion variant breakpoints." (PMID 37323575, 2023). "Eml4-Alk mice were assessed at 12 weeks post tumor induction, at which point the lungs contain multiple lung adenocarcinoma lesions." (PMID 36192379, 2022). "After a series of imaging examinations and needle biopsy, the patient was diagnosed as stage IV lung adenocarcinoma with multiple liver and bone metastases (EML4-ALK fusion, PD-L1 TPS 80%)." (PMID 35984185, 2022). "In this case report, we identified a novel non-reciprocal ALK fusion: ALK-grancalcin (GCA) (A19: intragenic) and EML4-ALK (E20: A20) by next-generation sequencing (NGS) in a male lung adenocarcinoma patient who was staged as IIIB-N2 after surgery." (PMID 35070986, 2022). "Here, we report the first case of a female patient with a diagnosis of stage IV lung adenocarcinoma harboring the EML4::NTRK3 gene fusion, and successfully treated with entrectinib." (PMID 36419889, 2022). "In this study, we investigated the histopathological features and clinical characteristics of patients with lung adenocarcinomas who harbored the EML4-ALK translocation in 251 lung resection (203 cases) and metastasectomy (48 cases) specimens." (PMID 32876329, 2021). "Correlative analyses were performed between the EML4-ALK mutation, the IGFR1, TTF1, and NapsinA expression, and the clinicopathologic factors in lung adenocarcinomas." (PMID 32876329, 2021). "EML4/ALK fusion-positive lung adenocarcinoma was predicted to be borderline more sensitive to Alectinib (p = 0.0632) and EML4/ALK or ROS1 fusion-positive lung adenocarcinoma was predicted to be more sensitive to Crizotinib (p = 0.044)." (PMID 34548481, 2021). "Material and Method: In this study, we analyzed the EML4-ALK mutation using the FISH and IHC techniques in 251 lung adenocarcinoma (203 primary resections, 48 metastasectomies) cases." (PMID 32876329, 2021). "Patients with lung adenocarcinoma harboring EML4-ALK rearrangements respond well to multiple ALK tyrosine kinase inhibitors (TKIs)." (PMID 33663128, 2021). "EML4-ALK translocations are observed in 5% of patients with lung adenocarcinoma, more frequently in those with the acinar, solid, or signet cell patterns." (PMID 33922215, 2021). "The aim of this study was to determine the EML4-ALK mutation and IGFR1 expression in lung adenocarcinoma and analyze their prognostic value." (PMID 32876329, 2021). "Here, we reported a case of patient who diagnosed with multifocal lung adenocarcinomas exhibiting both EGFR mutation and EML4-ALK rearrangement, in order to give some helpful advices for the clinical practice." (PMID 32375829, 2020). "Here we report a rare double ALK fusion variant, EML4-ALK and CDK15-ALK in a patient with lung adenocarcinoma who responded well to crizotinib." (PMID 33157918, 2020). "In summary, we represented a rare double ALK fusion composed of a classic fusion variant of EML4-ALK and a newly discovered CDK15-ALK in a lung adenocarcinoma." (PMID 33157918, 2020). "Post‐therapy specimens demonstrated PD‐L1 heterogeneity and an acyl glycerol kinase to B‐rapidly accelerated fibrosarcoma (AGK‐BRAF) fusion in a patient with an EML4‐ALK–positive lung adenocarcinoma as a potential resistance mechanism to ALK inhibitor therapy." (PMID 31747139, 2020).
lung adenocarcinoma (continued). "qRT-PCR successfully identified EML4-ALK fusion rearrangement in direct smear preparations of lung adenocarcinoma." (PMID 33425389, 2020). "Together, we identified a rare double ALK fusion variant, EML4-ALK and CDK15-ALK, in a patient with lung adenocarcinoma." (PMID 33157918, 2020). "KEY POINTS: A lung adenocarcinoma patient harboring concurrent NLRC4-ALK and EML4-ALK fusion mutations benefited from crizotinib after surgery." (PMID 32212216, 2020). "These circulating EV-RNA levels have been found to correlate with disease progression of EML4-ALK-translocated lung adenocarcinoma in patients prescribed ALK-TKI treatment." (PMID 30658414, 2019). "Other studies have also reported that lung adenocarcinoma combined with PE is related to a hypercoagulable state and EML4/ALK rearrangement in these patients." (PMID 31568496, 2019). "Although EML4-ALK fusion occurs in only 3–5% of lung adenocarcinomas, it is a therapeutic target in non-small cell lung cancer (NSCLC)." (PMID 30658414, 2019). "The fusion gene of EML4-ALK was discovered in lung adenocarcinoma in 2007; since then, fusion alterations of ALK, RET, and ROS1 genes have been found in about 4–7% of patients with lung adenocarcinoma." (PMID 31083279, 2019). "Because both A549 and Panc-1 are KRAS mutant cancer cell lines, we next checked the effects of COPS5 knock-down in H1650 or H2228 lung adenocarcinoma cell lines, which has an EGFR mutation or EML4-ALK fusion, respectively." (PMID 29755680, 2018). "ALK-fusion genes have been observed in anaplastic large cell lymphomas (ALCLs) as a nucleophosmin 1 (NPM1)-to-ALK fusion gene, and in lung adenocarcinomas (lung ADCs) as an EML4-to-ALK fusion gene." (PMID 29760954, 2018). "Other top recurrent fusions include EML4–ALK in lung adenocarcinoma (LUAD; 1.0%), CCDC6–RET in THCA (4.2%), and FGFR2–BICC1 in cholangiocarcinoma (CHOL; 5.6%)." (PMID 29617662, 2018). "Analogous to CML, these kinase fusion genes can also be therapeutically targeted, a key example of which is the EML4-ALK fusion gene seen in 3–7% of patients with adenocarcinoma of the lung." (PMID 29654269, 2018). "Identification of EML4-ALK fusion genes in lung adenocarcinoma has led to the application of ALK inhibitors for the treatment of lung adenocarcinoma with EML4-ALK fusions." (PMID 28636652, 2017). "In this paper we performed an accurate literature review and we reported two new cases of patients diagnosed with lung adenocarcinoma, exhibiting both EGFR mutation and EML4-ALK rearrangement." (PMID 28938691, 2017). "In 2007 Soda M etc. firstly discovered the EML4-ALK fusion gene from a 62-year-old patient with lung adenocarcinoma and confirmed EML4-ALK carcinogenicity in mice." (PMID 28915704, 2017). "The EML4-ALK fusion protein is expressed in 2–9% of lung adenocarcinomas, and has also been identified in breast and colorectal cancers." (PMID 28872581, 2017). "We employed combined testing for fusions and mutations and detected fusion of EML4 exon 13 with ALK exon 20, which is one of the most common fusion variants in lung adenocarcinomas (variant 1)." (PMID 27863497, 2016). "In conclusion, metastatic thyroid tumours from EML4-ALK-positive lung adenocarcinoma are relatively rare, so it is important to prove the thyroid tumour to be metastatic." (PMID 27872133, 2016). "EML4-ALK-positive lung adenocarcinoma cell lines H3122 and H2228 were sensitive to ALK inhibitors crizotinib and NMS-E628." (PMID 27078848, 2016). "In this report, we have shown relatively rare case with potentially aggressive EML4-ALK-positive lung adenocarcinoma showing almost pure GGN." (PMID 26964537, 2016). "Compared with overall gene alterations in Asian lung adenocarcinoma patients, EML4-ALK alterations in our study were relatively increased, and EGFR mutations were relatively reduced." (PMID 26332764, 2015).
lung adenocarcinoma (continued). "A clinical response to EGFR-TKIs in patients with EML4-ALK-positive lung adenocarcinoma has been previously observed in cases that harbour a coexisting EGFR mutation and EML4-ALK translocation." (PMID 25788996, 2015). "EML4-ALK fusion was recently identified as a novel molecular abnormality in about 5% of lung adenocarcinomas 7,8." (PMID 24403104, 2014). "Adenocarcinoma of the lung with EML4-ALK translocation is a rare subtype of Non Small-Cell Lung Cancer (NSCLC) that has recently shown to benefit from treatment with crizotinib." (PMID 25178493, 2014). "A previous study has reported that the EML4-ALK-positive lung adenocarcinomas are characterized as less-differentiated." (PMID 25407901, 2014). "Consistent with previous studies, we detected EML4–ALK fusions in ~1% (5/513) of lung adenocarcinoma samples, multiple ALK fusions, including a single STRN–ALK fusion, in thyroid cancer (3/498) and one in papillary renal carcinoma." (PMID 25204415, 2014). "In recent years, rearrangements of the anaplastic large cell kinase (ALK) gene have been discovered in approximately 5% of lung adenocarcinomas, resulting in the constitutive expression of a fusion protein - most commonly EML4-ALK - with oncogenic activity." (PMID 24422905, 2014). "Although other histological sub-types rarely contain EML4-ALK rearrangements, lung adenocarcinoma has been reported to be the major type showing EML4-ALK translocations." (PMID 27234388, 2013). "Reported herein is a case of synchronous EML4-ALK positive lung adenocarcinoma and adenocarcinoma in situ in the bilateral lungs of a 55-year-old Japanese woman." (PMID 23617234, 2013). "The woman had EML4-ALK positive lung adenocarcinoma in the right lower lung while adenocarcinoma in situ in the left upper lung." (PMID 23617234, 2013). "The woman had EML4-ALK positive lung adenocarcinoma in the right lower lung while adenocarcinoma in situ in the left upper lung, which was EML4-ALK negative." (PMID 23617234, 2013). "The mucinous cribriform histology of the HE stained specimen made us suspicious of EML4-ALK positive lung adenocarcinoma." (PMID 23617234, 2013). "A subset of lung adenocarcinomas harboring an EML4-ALK fusion gene resulting in dominant oncogenic activity has emerged as a target for specific therapy." (PMID 23289484, 2013). "The majority of Caucasian lung adenocarcinoma harboring EML4-ALK show the signet-ring cell histology, whereas the acinar pattern is pre-dominant in ALK-positive Asian adenocarcinomas." (PMID 27234388, 2013). "EML4-ALK positive lung adenocarcinoma typically occurs in young subjects with non- or low smoking habits." (PMID 23617234, 2013). "In 2007, a translocation between echinoderm microtubule-associated protein-like 4 (EML4) and ALK was identified in a subset of lung adenocarcinomas." (PMID 22263108, 2012). "Examples include the use of epidermal growth factor receptor (EGFR) inhibitors such as gefitinib and erlotinib for lung adenocarcinomas bearing EGFR mutations, and of ALK inhibitors such as crizotinib for lung adenocarcinomas bearing EML4-ALK translocations." (PMID 21666749, 2011). "It usually occurs in light or non-smokers with lung adenocarcinoma, and the most frequent fusion is the echinoderm microtubule-associated protein-like 4 gene (EML4)-ALK variant." (PMID 40297141, 2025). "This case report details the management of a 33-year-old male never-smoker diagnosed with stage III lung adenocarcinoma harboring an Echinoderm microtubule-associated protein-like 4 (EML4)-anaplastic lymphoma kinase (ALK) fusion gene." (PMID 41293380, 2025). "In addition, a patient with lung adenocarcinoma concomitant EGFR mutations and EML4-ALK fusion benefited from combination treatment with EGFR-TKIs and ALK-TKIs." (PMID 40052122, 2025). "Herein we report a 45-year-old Asian woman diagnosed with EML4-ALK rearranged lung adenocarcinoma." (PMID 38961982, 2024).